GSTP1 (glutathione S-transferase pi 1)
Diseases named in the same sentence as GSTP1 in open-access papers (continued):
Sharing a sentence is not in itself a finding about the gene and the disease.
cancer (continued). "The promoter region of GSTP1, encoding for Glutathione S-transferase P1, has been found to be hyper methylated in about 50% of cancer tissues including HCC." (PMID 29597259, 2018). "In several types of cancers, overexpression of GSTP1 was associated with decreased treatment response and survival." (PMID 29116019, 2017). "Abnormally high methylation inactivates GSTP1 and is associated with reduced cell detoxification and anti-cancer enzyme activity." (PMID 28325946, 2017). "Genetic and epigenetic variability in the promoter region of GSTP1 also affects gene expression and influences susceptibility to several types of cancer." (PMID 29046813, 2017). "Previous studies have investigated the association between the GSTP1 polymorphism and treatment outcomes in other cancers." (PMID 29069838, 2017). "GSTP1 (hyper)methylation is a hallmark of carcinogenesis and the most common molecular alteration in human cancer." (PMID 27965466, 2017). "GSTP1 acts to protect cells from DNA damage and the development of cancer, as it is associated with the detoxification, metabolism and elimination of potentially genotoxic exogenous compounds." (PMID 25738352, 2015). "Elevated expression of the GSTP1 gene or protein has been reported to correlate with drug resistance in human cancers, and high levels have been associated with poor prognosis in breast and colon cancer." (PMID 26393654, 2015). "In humans, early loss of Gstp1 expression due to promoter hypermethylation results in increased cancer susceptibility." (PMID 25846707, 2015). "Lower risk of the disease progression and chemoresistance was found in GSTP1 105Val allele carriers and also in cancer patients with at least one GSTP1 105Ile allele." (PMID 24919441, 2014). "Apart from aberrant protein expression levels, attention has been directed toward the association of GSTP1 polymorphisms with the risk of cancers." (PMID 25317080, 2014). "In contrast, knockout experiences in mice showed that loss of GSTP1 expression leads to increased cancer susceptibility." (PMID 25076909, 2014). "Epigenetically mediated GSTP1 silencing is associated with enhanced cancer susceptibility by decreasing its “caretaker” gene function, which tends to promote neoplastic transformation allowing cells to acquire additional alterations." (PMID 25076909, 2014). "In fact, the use of GSTP1 knockout mice demonstrated that loss of GSTP1 expression increases sensitivity to metabolic or environmental toxins and promotes mutations and cancer development (Coughlin and Hall, 2002a,b)." (PMID 25076909, 2014). "It should be noted that GSTP1 Ile105Val (rs1695) polymorphism was also found to be associated with the efficacy of cancer chemotherapy." (PMID 24919441, 2014). "Our results demonstrated that there was a moderate association between the GSTP1 341C>T polymorphism and cancer risk in Asian population." (PMID 23437223, 2013). "Numerous studies report altered expression of GSTP1 in cancers, and it is implicated in resistance to chemotherapy." (PMID 23873296, 2013). "Among the GSTs, the association of the GSTM1, GSTT1 and GSTP1 genotypes with their individual susceptibilities to cancer has been extensively studied." (PMID 23717494, 2013). "The 341C>T polymorphism of the GSTP1 has been implicated in cancer risk through cutting down its metabolic detoxification activities." (PMID 23437223, 2013). "The GSTP1 gene is located on chromosome 11, and the single nucleotide polymorphisms (SNPs) in this gene are known to cause genetic damage and increased cancer risk." (PMID 23717494, 2013). "A large number of studies have investigated the role of GSTP1 polymorphism in the etiology of cancer of various organs, including lung, breast, colorectal, bladder, prostate and so on." (PMID 23437223, 2013). "Previous conclusions of numerous studies on the association between the GSTP1 341C>T polymorphism and cancer risk remain conflicting and contradictory." (PMID 23437223, 2013).
cancer (continued). "In recent years, plenty of meta-analysis studies were extensively carried out to quantitatively evaluate the association between GSTP1 and cancer susceptibility." (PMID 23437223, 2013). "Some studies have observed a different relation between the GSTP1 polymorphism and an increased risk for oral, breast, colorectal, prostate and lung cancers." (PMID 23077566, 2012). "GSTP1 promoter region inactivation by hypermethylation is a common event in cancer and this epigenetic modification is often linked with a loss of GSTP1 expression." (PMID 23226781, 2012). "Extensive molecular epidemiological studies indicate that the GSTP1 variant is more likely to lead to development of cancer than its wild type." (PMID 23144854, 2012). "The polymorphisms in GSTM1 and GSTT1 have been investigated in cancer for a long time; however, only recently have some studies investigated the association of various cancers with GSTP1 variants." (PMID 23077566, 2012). "The association of various lifestyle factors with GSTP1 promoter hypermethylation was also studied, including age, smoking status, age of menarche onset, contraceptive use, family history of cancer, number of children, ER and PR status and alcohol intake." (PMID 23226781, 2012). "GSTP1 promoter hypermethylation and loss of expression are frequently observed in various types of carcinoma." (PMID 23226781, 2012). "In vitro cDNA expression study suggests that GSTP1 with 105Val variant results in a protein with reduced enzyme activity, however it is reported to play an unlikely role for smoking-related cancers." (PMID 22206016, 2011). "The GST-pi gene has four functional polymorphisms (GSTP1*A, GSTP1*B, GSTP1*C, and GSTP1*D), with each allelic genotype having different treatment response outcomes among individual cancer patients." (PMID 20717533, 2010). "Using GSTP1-deficient MCF-7 cancer cells and siRNA interference targeting GSTP1 in HaCaT keratinocytes expressing either wild-type or mutant HPV-16 E7, we uncovered a pivotal role for GSTP1 in the pro-survival program elicited by its binding with HPV-16 E7." (PMID 19826491, 2009). "It is plausible that polymorphism at the GSTP1 locus can play an important role in the susceptibility to different types of cancer." (PMID 19265530, 2009). "In addition to its diagnostic potential, GSTP1 hypermethylation has been implicated as a prognostic marker in various cancers, including HCC." (PMID 40051701, 2025). "The expression of certain glutathione S-transferase isoenzymes (e.g., GSTP1) is elevated in many types of cancer and is associated with the promotion of cancer development (through apoptosis inhibition and uncontrolled cell proliferation) as well as with multidrug resistance (MDR)." (PMID 40806333, 2025). "The combined GSTM1 null and GSTT1 null led to a significant risk; similarly, the combined GSTM1 null and GSTP1 Ile/Val or Val/Val genotypes as well as the GSTT1 null and GSTP1 Ile/Val or Val/Val genotypes significantly increased the individuals’ susceptibility to cancer." (PMID 39595582, 2024). "And it was shown in this study that GSTM1, GSTT1, and GSTP1 polymorphisms, alone or in combination with smoking or drinking, might affect the overall cancer risks differently, and the effects might be related to ethnicities." (PMID 38579033, 2024). "The loss of GSTP1, primarily through epigenetic silencing, has been reported in various cancers, and could make proximal tubule cells in the kidney, which metabolise these compounds, more vulnerable to genotoxic stress." (PMID 39592856, 2024). "Otherwise, the representativeness might be stronger to further explore the interaction between GSTM1, GSTT1 and GSTP1 polymorphisms and cancers among drinkers." (PMID 38579033, 2024). "GSTP1 effectively defends cells against cancer‐causing and electrophilic substances." (PMID 37901797, 2023).
cancer (continued). "Apart from inhibiting GST activity, NBDHEX can also induce the dissociation of GSTP1 from its complex with c‐Jun N‐terminal kinase or tumor necrosis factor receptor‐associated factor 2 thereby promoting the activation of apoptosis pathways in cancer cells." (PMID 37229486, 2023). "However, stratifying by race, the percentage of any TMA spot with cancer cells staining positive for GSTP1 was comparable in those with PTEN loss and PTEN intact in Black men and in White men." (PMID 34191807, 2021). "Besides the results on the effect of novel GSTP1 polymorphism on the overall survival of patients with PC, it would be beneficial to investigate its potential association with cancer-specific survival in a larger cohort." (PMID 33937322, 2021). "In particular, methylation of GSTP1, which encodes an enzyme that is considered to play a key role in cancer susceptibility, has been detected in various cancers but shows high specificity for PCa and has been suggested to serve as a clinical biomarker for PCa diagnosis." (PMID 34201712, 2021). "We suggest that GSTP1, along with a combination of other biomarkers, may identify a high-risk population that is susceptible to developing cancer." (PMID 33946704, 2021). "To confirm cancer-cell content in our low-volume primary tissue specimen, we have developed a multiplex epigenetic biomarker assay to detect promoter methylation of PC-associated genes including GSTP1, RASSF1, RARb and APC." (PMID 34581895, 2021). "Interestingly, in some cancer cell lines, enhanced GSTP1 enzymatic activity is very often associated with an increase in GSTP1 gene expression, increased GSTP1-1 protein level, or both." (PMID 33193885, 2020). "The human cytosolic GSTP1 has been linked to inactivation of many agents including anticancer drugs, and some have found that GSTP1 overexpression confers chemoresistance in various cancer types." (PMID 32961800, 2020). "Similarly, GSTP1*Val (rs1138272) allele carriers had a nearly 5-fold higher risk of cancer development compared to individulas with both referent alleles (OR = 4.93, 95%CI: 2.89–8.40, p < 0.001)." (PMID 32183092, 2020). "Although many studies have shown associations between GSTP1 polymorphisms and various types of cancer, the results of a few studies investigating the associations between GC risk and GSTP1 genetic variants are inconsistent across geographic areas and diverse populations." (PMID 33634021, 2020). "In summary, the TT genotype of the GSTP1 rs1138272 polymorphism may be associated with an increased susceptibility to cancer." (PMID 30740061, 2018). "Therefore, the rs1138272 polymorphism of the GSTP1 gene appears to be correlated with an increased risk of cancer in the Asian and African populations." (PMID 30740061, 2018). "Interestingly, in some cancer cell lines, the enhanced GSTP1 enzymatic activity is very often associated with an increase in GSTP1 gene expression, increased GSTP1-1 protein level, or both of them." (PMID 29358310, 2018). "In dogs, exposure to environmental chemicals that may be GSTP1 substrates is associated with cancer." (PMID 29046813, 2017). "Consequently, there is a possibility that smokers carrying the GSTM1 or GSTP1 or GSTM3 risk genotype will be susceptible to cancer if the DNA adducts remain unrepaired." (PMID 24416175, 2014). "Interestingly, hydralazine's ability to demethylate the promoter region of tumor-suppressor genes, including GSTP1, RARβ2 and p16, causing its re-expression has been documented in several cancers." (PMID 24797896, 2014). "Accordingly, we speculated that GSTP1 341C>T polymorphism might also be a risk factor in the genesis and development of cancer." (PMID 23437223, 2013). "Stratified analyses of the GSTP1 341C>T polymorphism on cancer risk." (PMID 23437223, 2013). "In conclusion, our meta-analysis suggests that the GSTP1 341C>T polymorphism may implicate genetic susceptibility to cancer." (PMID 23437223, 2013).
cancer (continued). "Furthermore, investigation of the impact of gene-gene and gene-environment interactions on the GSTP1 341C>T polymorphism and cancer risk is necessary for providing a better comprehensive understanding of the association." (PMID 23437223, 2013). "GSTP1 exert varying effects on different organs, and the carcinogenic mechanism difference may account for varied cancer risk." (PMID 23437223, 2013). "GSTP1 polymorphisms have been evaluated as risk factors for cancers in a number of studies." (PMID 23144854, 2012). "Since it is conceivable that the GSTP1 gene might confer susceptibility to non-cancer disease, the genotype frequencies might be different between population-based and hospital-based controls, and this might introduce heterogeneity among studies." (PMID 23144854, 2012). "Thus, the hypermethylation of the promoter of the GSTP1 gene has been associated with various cancers, including HCC." (PMID 22536438, 2012). "The GSTM1, GSTT1 and GSTP1 polymorphisms might be involved in inactivation of procarcinogens that contribute to the genesis and progression of cancers." (PMID 23189206, 2012). "The GSTM1, GSTT1 and GSTP1 members of the multigene family are candidate cancer-predisposing genes." (PMID 19265530, 2009). "Association of the GSTP1 Val allele with cancer could be expected since the conversion of the amino acid at codon 105 from isoleucine to valine substantially lowers activity of the altered enzyme." (PMID 19265530, 2009). "Herein, we sought to construct risk calculators based on cancer biomarkers, enabling more accurate discrimination among patients which may benefit from active interventions.Ki67 immunoscore, GSTP1 and KLF8 promoter methylation levels (me) were assessed in PCa tissues." (PMID 39090707, 2024). "However, subgroup analysis indicated that GSTP1 (AG + GG) variations might reduce the risk of cancers among Caucasian smokers." (PMID 38579033, 2024). "Additionally, modulating GSTP1 could protect normal cells or increase cancer cell susceptibility to ferroptosis." (PMID 39697237, 2024). "In addition, the relationship between GSTP1 gene polymorphism and adverse reactions related to chemotherapy drugs may be inconsistent in different cancer types and different treatment regimens." (PMID 35729577, 2022). "GSTP1 is a recognized tumor suppressor that interacts and modulates several pathways involving cell growth, differentiation, and cell death, and as such, its association with cancer has been vast, featuring a plethora of studies linking its polymorphisms and hypermethylation with cancer." (PMID 36553191, 2022). "Moreover, the same GSTP1 polymorphism associated with larger tumor size may contribute to cancer progression and aggressiveness." (PMID 31357662, 2019). "In addition, we found that the GSTP1 rs1138272 polymorphism may be associated with an increased risk of cancer in the African population." (PMID 30740061, 2018). "A GSTP1 polymorphism (GSTP1 Ile105Val), which has a seven fold higher efficiency, has been linked to a reduced survival rate in cancer patients further emphasizing that while glutathione may be able to reduce treatment toxicity, it can potentially also confer an advantage to the tumor cells as well." (PMID 25869442, 2015). "Inhibition of the activity of GSTP1 may lead to increased DNA damage and susceptibility to cancer." (PMID 25738352, 2015). "Interestingly, our study shows that variant GSTT1 and GSTP1 genotypes were associated with reduced cancer risk, which in turn may suggest a complex role of these functional polymorphisms in BC development." (PMID 24919441, 2014). "In previous studies, constitutive GSTP1 knockdown was shown to reduce cell viability and proliferation in pancreatic and other cancers." (PMID 40719618, 2025). "Research suggests that curcumin-induced inactivation of GSTP1 leads to the activation of nuclear factor-κB (NF-κB) and subsequent anti-cancer effects in treated cells." (PMID 40290119, 2025).
cancer (continued). "Chemotherapeutic medicines can be detoxified by them as well, for instance, GSTP1 contributes to chemoresistance in ovarian and other forms of cancer." (PMID 40290119, 2025). "For instance, the small molecule inhibitor TLK199 has shown promise in sensitizing cancer cells to chemotherapy by selectively targeting GSTP1, improving the efficacy of drugs like cisplatin in ovarian cancer models." (PMID 39954068, 2025). "Glutathione S-transferase P1 (GSTP1) plays a significant role in cancer progression and chemotherapy resistance, with its overexpression diminishing chemotherapeutic efficacy across various tumor types." (PMID 39954068, 2025). "More recently, an alternative ferroptosis regulatory mechanism involving glutathione S-transferase P1 (GSTP1) has been identified in cancer models both in vitro and in vivo." (PMID 41301848, 2025). "The second phase represented GSTP1 (encodes glutathione S-transferase π) and NNMT (encodes nicotinamide N-methyl transferase) expression, which increased in all stages of cancer development." (PMID 41465541, 2025). "Given GSTP1’s prominent role in drug resistance, targeting this enzyme has emerged as a promising strategy in cancer therapy." (PMID 39954068, 2025). "While several other small-molecule inhibitors have been developed to target GSTP1, challenges remain in finding potent and selective compounds capable of effectively inhibiting this enzyme in cancer cells." (PMID 39954068, 2025). "The expression of glutathione S-transferase P1 (GSTP1) enzyme increases in cancer cells, leading to anticancer drug resistance." (PMID 40014124, 2025). "GSTP1 is overexpressed in multiple cancers, including PDAC, where its high expression is associated with tumor progression and poor clinical outcomes." (PMID 40719618, 2025). "For several remaining top genes, functional validation pinpointed a causal role in carcinogenesis, but in specific cancers other than KIRC (SCIN, HAGLR, GSTP1)." (PMID 41188181, 2025). "This, in turn, enhances the antioxidant and detoxification capabilities of cancer cells by increasing GSTP1 protein levels." (PMID 41226811, 2025). "It has been applied in various therapeutic contexts, particularly in cancer treatments, due to its ability to sensitize tumor cells to chemotherapy by inhibiting GSTP1, which is involved in drug resistance." (PMID 39954068, 2025). "The CIBERSORT results indicated a significant correlation between the levels of immune cell infiltration and GSTP1 expression across most types of cancers." (PMID 40555906, 2025). "This study highlights 6-thio-dG and its dimer as promising GSTP1 inhibitors with the potential to counteract chemoresistance in cancer." (PMID 39954068, 2025). "We investigated the correlation between GSTP1 expression and the prognosis of a wide range of cancer patients, including overall survival (OS) and progression-free interval (PFI) data." (PMID 40555906, 2025). "GSTP1 is frequently overexpressed in various cancers, where it serves as a protective mechanism for cancer cells by detoxifying reactive molecules and reducing oxidative stress." (PMID 39954068, 2025). "Polymorphism at codon 105 in exon 5 and codon 114 in exon 6 of GSTP1 results in reduced enzymatic detoxification activity, which contributes to the development of many cancers." (PMID 40847407, 2025). "Continued investigation into GSTP1's regulatory networks will be crucial for developing effective treatments for this highly lethal cancer." (PMID 40719618, 2025). "The role of GSTP1 in promoting drug resistance and tumor survival makes it a promising therapeutic target for cancer treatment." (PMID 39954068, 2025).